POLE (DNA polymerase epsilon, catalytic subunit)
Diseases named in the same sentence as POLE in open-access papers (continued):
Sharing a sentence is not in itself a finding about the gene and the disease.
endometrial cancer (continued). "Therefore, the negative correlation between age and mutation loads in endometrial cancer could be explained by the presence of hypermutated tumours in younger patients, which are associated with MSI-H and POLE/POLD1 mutations." (PMID 33879792, 2021). "In our study, 8 patients were identified with pathogenic or likely pathogenic germline mutations in non-Lynch syndrome genes (MUTYH, GALNT 12, POLE, MPL, ATM, and ERCC4), which indicated that there may be other genes outside of Lynch syndrome associated with endometrial cancer." (PMID 30886832, 2019). "In addition, we identified 2 patients who had a deleterious germline mutation in Lynch syndrome genes (MLH1 and MLH2), and another 8 patients harbored germline mutations of 6 non-Lynch syndrome genes (MUTYH, GALNT12, POLE, MPL, ATM, and ERCC4) which may be associated with endometrial cancer." (PMID 30886832, 2019). "Thus, the POLE-MSI signature is not exclusive to endometrial tumors, although the frequency is much reduced in non-endometrial (<1% of samples) compared to endometrial cancers (19/531 samples, ~3.6%)." (PMID 29717118, 2018).
colorectal cancer (129 papers, 2013 to 2026). A primary or metastatic malignant neoplasm that affects the colon or rectum. "In this study, we analyzed NGS data from 181 colorectal cancer patients and identified five cases with POLE mutations, two of which were pathogenic based on ultra-hypermutation and molecular features." (PMID 40310397, 2025). "DNA polymerase epsilon (POLE) mutations occur at a higher rate than average-onset colorectal cancer (AOCRC)." (PMID 40710181, 2025). "Recent studies in colorectal cancer have demonstrated that POLE mutations can reshape the mRNA expression landscape, supporting the concept of mini-driver genes that exert subtle yet functionally relevant transcriptional effects across multiple pathways." (PMID 41226475, 2025). "POLE alterations are linked to genome instability and are associated with the prognosis and development and onset of tumors, including colorectal cancer (CRC) and EC, which results in an “ultramutated” phenotype." (PMID 40936703, 2025). "This case illustrates a profound and sustained response to immune checkpoint inhibition in a patient with early-onset, microsatellite-stable, POLE-mutated colorectal cancer." (PMID 40710181, 2025). "This study focused on a Japanese colorectal cancer cohort, and POLE mutations were identified in 4 out of 1052 patients, indicating a slightly lower frequency." (PMID 40310397, 2025). "This POLE mutation has already been reported in colorectal cancer as being similar to known POLE hotspot mutations." (PMID 39865420, 2025). "In 2016, a multicenter study was conducted involving approximately 6500 colorectal cancer patients to identify those with somatic POLE mutations and to perform clinicopathological analysis." (PMID 40310397, 2025). "For colorectal cancer, the estimated risk by age 70 is around 90% in POLE heterozygotes versus 50% in POLD1 carriers." (PMID 41487566, 2025). "Germline POLE alterations are linked to genome instability and are associated with onset of hereditary tumors, including colorectal cancer and EC." (PMID 40936703, 2025). "We analyzed the distribution of APC mutations in colorectal cancers in 100kGP with pathogenic POLE mutations or MSI, mirroring the analysis carried out for MSS colorectal cancers." (PMID 41091816, 2025). "Within the epidemiological landscape, POLE exonuclease domain mutations are identified in only 0.3–0.7% of colorectal cancer and polyposis cases." (PMID 40710181, 2025). "Here we use an artificial intelligence algorithm to determine what other mutations co-occur with POLe mutations in colorectal cancers." (PMID 40806338, 2025). "Overall, in colorectal cancer, 77.8% of the POLE variants occurred in POLE ExoD signature sequence contexts." (PMID 38282550, 2024). "Decomposition of the mutations identified in epithelial cells from hypermutated colorectal cancer samples using COSMIC signatures revealed a strong contribution of signatures associated with POLE and MMR deficiency." (PMID 37414936, 2024). "Some of these B-family DNA polymerase members, e.g. POLD1 and POLE, are already known to be mutated in some familial colorectal carcinomas and adenomas." (PMID 39128273, 2024). "Exonuclease domain mutation (EDM) in polymerase epsilon (POLE)-mutated colorectal cancer patients is characterized by specific clinical features and a very high tumor mutation burden (TMB)." (PMID 37593074, 2023). "It is estimated that pathogenic variants in the exonuclease domain of POLE are found in 2–8% of colorectal cancers." (PMID 37239414, 2023). "We reported three novel likely pathogenic mutations in POLE: c.802-2A>G, c.6665_6666del, and c.799C>T in patients with colorectal cancer, ovarian cancer, and pancreatic cancer, respectively." (PMID 38201513, 2023). "It is well known that colorectal cancer with dmmr/msi-h phenotype is sensitive to immunotherapy, yet the POLE mutation is the MSS phenotype in colorectal tumors but is also an effective target for immunotherapy." (PMID 37007102, 2023).
colorectal cancer (continued). "In accordance with the tumor spectrum initially and most commonly described in PPAP patients, we observed colorectal cancer in four of 10 (40%) families with rare POLE/POLD1 germline variants." (PMID 37990341, 2023). "Colorectal cancers driven by somatic POLE mutations occur in 1–2% of colorectal cancers; POLD1 mutations are very uncommon." (PMID 36672501, 2023). "Colorectal cancer patients with PolE mutations are typically diagnosed younger than patients with wild-type PolE (median of 54.5 years vs. 67.2 years, p < 0.0001) and at an earlier disease stage (p = 0.006, x2 test for trend)." (PMID 35326618, 2022). "It has been recently reported that germline POLE mutations are risk factors for colorectal cancer (CRC) and other tumor types, including endometrial cancer (EC)." (PMID 35624529, 2022). "Germline mutations in the exonuclease domain of POLD1 and POLE affect the proofreading abilities of these polymerases, predispose to multiple colorectal carcinomas and adenomas, and generate polymerase proofreading-associated polyposis (PPAP)." (PMID 35207516, 2022). "POLE mutations, which lead to an ultramutated phenotype in colorectal cancer (CRC), have been reported as a promising marker in immunotherapy." (PMID 33125191, 2021). "Researchers also identified a unique subclass of colorectal cancer characterized by hypermutation associated with the POLE mutation." (PMID 33898421, 2021). "The polymerase proofreading-associated polyposis syndrome (PPAP) with missense mutations in the POLE- or POLD1-gene was recently described as cause of a new polyposis syndrome with development of colorectal cancers." (PMID 34118935, 2021). "Cancers of the colorectum and endometrium are the predominant types associated with germline and somatic POLE/POLD1 mutations." (PMID 34594041, 2021). "The principal difficulty encountered during this analysis concerned p.Leu424Val POLE variant, observed in multiple individuals with either an attenuated polyposis phenotype or a history of colorectal cancer." (PMID 34749799, 2021). "The main causes of TMB-H in colorectal cancer include POLE/POLD1 deficiencies and MSI-H resulting from MMR mutation or MLH1 promoter hypermethylation." (PMID 33194656, 2020). "The POLE variant, c.1089C>A, p.(Asn363Lys) was identified in a patient with three metachronous colorectal cancers from age 28 and turned out to be de novo." (PMID 33193653, 2020). "The mutational spectrum of the different POLE mutants was compared and validated in a large cohort of 7,345 colorectal cancer samples from additional whole exome/target capture sequencing data." (PMID 32012149, 2020). "The analyzed colorectal cancer cases with pathogenic mutation in POLE, POLD1 and MSI were all identified to have signature a, which was characterized by structural deletion with size between 1 K–10 K." (PMID 32245405, 2020). "This is expected as SBS10a is associated with POLE mutations and SBS28 commonly occurs in colorectal cancers with POLE mutations." (PMID 33293579, 2020). "In this study, we first characterized 53 whole genomes of colorectal cancer, which harbor different POLE exonuclease domain somatic mutations (n = 9) or are POLE wild-type (n = 44)." (PMID 32012149, 2020). "Somatic mutations of POLE exonuclease domain are frequently enriched in brain, uterine and colorectal cancer, and patients with POLE dysfunction usually have significantly better prognosis and require less intensive treatment." (PMID 32012149, 2020). "First identified and reported in 2–6% of colorectal carcinomas, POLE mutations were also noted at frequencies of 6–9% amongst uterine corpus endometrial cancers and in gastric adenocarcinoma." (PMID 32838755, 2020).
colorectal cancer (continued). "Germline mutations in the exonuclease domains of POLE were associated with a familial predisposition and increased risk of colorectal cancer and giant cell glioblastoma." (PMID 31864301, 2019). "A recent study of the timing of POLE mutations established that these changes occur early in carcinogenesis and are detectable in preneoplastic lesions of both endometrial and colorectal cancers." (PMID 31747945, 2019). "POLE mutations are associated with an ultramutated phenotype and are reported in 1–2% of colorectal cancers." (PMID 31139574, 2019). "A large retrospective study in colorectal cancer demonstrated that POLE-mutated tumours occur in younger patients more often than non-POLE-mutated tumours (median 54.5 years for POLE-mutated tumours vs. 67.2 years for non-POLE-mutated tumours)." (PMID 30917185, 2019). "Here, we investigated the clinicopathological and mutation profiles of colorectal cancer (CRC) with POLE mutations." (PMID 31240875, 2019). "Within our study cohort, only one patient had a pathogenic POLE R762W mutation previously identified in colorectal cancer affecting the catalytic domain of the enzyme." (PMID 31258846, 2019). "Collectively, these data indicate that somatic POLE mutations are early, quite possibly initiating, events in the endometrial and colorectal cancers in which they occur." (PMID 29604063, 2018). "Collectively, these data suggest that somatic POLE mutation occurs early in endometrial and colorectal cancers, and that its attendant mutator phenotype defines a distinct pathway of carcinogenesis from the initial stages of this process." (PMID 29604063, 2018). "Here, we have shown that pathogenic POLE mutations are detectable in non‐malignant precursors of endometrial and colorectal cancer." (PMID 29604063, 2018). "While POLE mutations are found in 7–12% of EC, they are also found in other malignancies including colorectal cancers, cancers of the brain, breast, pancreas and stomach, albeit at lower frequencies." (PMID 28344870, 2017). "For instance, in a colorectal carcinoma (TCGA-D5-6931) the WTSI Mutational Signature Framework determined 20.4 % of the mutational signature present was associated with a POLE hyper-mutator phenotype." (PMID 26899170, 2016). "The first predisposing mutation identified in POLE (c.1270C>G, p.Leu424Val) was associated with colorectal cancer only, but another mutation with a broader tumour spectrum (c.1089C>A, p.Asn363Lys) has recently been reported." (PMID 25860647, 2015). "This ultramutated carcinoma had a POLE V411L mutation previously implicated in ultramutated endometrial and colorectal carcinomas." (PMID 25916844, 2015). "This cancer had POLE V411L mutation that was characterized as one of the hotspot mutations in ultramutated endometrial and colorectal carcinomas." (PMID 25916844, 2015). "Recent molecular profiling studies reported a new class of ultramutated colorectal cancers (CRCs), which are caused by exonuclease domain mutations (EDMs) in DNA polymerase ε (POLE)." (PMID 25124163, 2014). "Clinical response to ICI treatment in MSS colorectal cancers with POLE mutations." (PMID 40873566, 2025). "However, consistent with other findings, POLE-mutated colorectal cancers were significantly associated with younger age, right-sided colon location, poor histological grade, early stage, and KRAS/NRAS/BRAF wild-type status." (PMID 40310397, 2025). "The landscape of colorectal cancers with POLe mutations has also been previously reported on." (PMID 40806338, 2025). "Moreover, most colorectal cancers with POLE/POLD1 mutations exhibit a microsatellite stable (MSS) phenotype." (PMID 40308511, 2025). "The hotspot somatic mutation observed in POLE occurred in the exonuclease domain of the encoded protein and has been reported in a small subset of microsatellite-stable and hypermutated colorectal carcinomas, affecting the proofreading activity of the enzyme during DNA replication." (PMID 40981433, 2025).
colorectal cancer (continued). "TMB refers to the quantity of mutations within a megabase of DNA (expressed as Mut/Mb) and, in the context of colorectal cancer, it tends to be highly correlated with microsatellite instability or detrimental mutations in the proofreading segments of the DNA polymerases POLE and POLD." (PMID 38792879, 2024). "Hypermutated colorectal cancer with POLE/POLD1 variants may benefit from therapy with immune checkpoint inhibitors (ICIs), providing new treatment opportunities for patients carrying POLE/POLD1 variants." (PMID 37990341, 2023). "This case reminds us that the existence of malignant tumors should be considered for patients with repeated intestinal leakage, and emphasizes the importance of gene detection in the treatment of malignant tumors and the significance of POLE mutations in colorectal cancer." (PMID 37007102, 2023). "In addition, several somatic POLE mutations in the exonuclease domain were also identified in colorectal cancers from a large database." (PMID 37175782, 2023). "Consistently, in the DFCI cohort, the highest prevalence of MMR/proof-reading polymerases mutations is in double BRAF and PIK3CA mutant colorectal cancers with the exception of POLE which shows the highest mutation prevalence in BRAF mutant cancers without PIK3CA mutations." (PMID 36079062, 2022). "For example, SBS10 and SBS7 mutations, which are associated with the hypermutated genomes of POLE-mutated colorectal cancers and melanoma, respectively, might have undergone distinct evolutionary trajectories." (PMID 35902761, 2022). "Summary of germline POLE mutations in colorectal cancer reported in published articles (2017–2020)." (PMID 36479248, 2022). "NTRK‐driven colorectal cancer patients demonstrated increased TMB (median = 53 mut/MB, 95% CI: 36.8–68.0 mut/MB), high microsatellite instability, and an enrichment for POLE/POLD1 mutations when compared to molecularly unstratified colorectal cancer population." (PMID 35506567, 2022). "Mutations in the POLE gene result in an ultra-hypermutated phenotype in colorectal cancer (CRC); however, the molecular characterisation of epigenetic alterations remains unclear." (PMID 34034807, 2021). "Moreover, POLE/POLD1 mutation was identified in 0.65–12.3% of colorectal cancer patients and was reported to occur more frequently in EO CRC patients." (PMID 33194656, 2020). "Finally, combining these datasets, we sought to identify associations between specific POLE mutants and the formation of driver mutation hotspots in colorectal cancer." (PMID 32012149, 2020). "Interestingly, this mutation (POLE p.314S > A) was predicted as colorectal carcinoma predisposing mutation in another study by our group (data unpublished)." (PMID 31866764, 2019). "However, screening of 389 colorectal adenomas from 261 patients revealed three (0.8% adenomas; 1.1% patients) with somatic POLE mutations, a frequency concordant with that found in colorectal cancers." (PMID 29604063, 2018). "We next examined the timing of POLE mutations in carcinogenesis in more detail by analysis of driver genes, including some that are known to be usually mutated early in the pathogenesis of endometrial or colorectal cancer." (PMID 29604063, 2018). "As somatic POLE mutations have been best characterized in endometrial and colorectal cancers, we first examined whether these mutations were present in precursors of these malignancies." (PMID 29604063, 2018). "Meanwhile, mutations in POLE has been reported to be associated with lesions in colon and rectum, and novel mutations in POLE detected by exome sequencing also seem to explain the cancer predisposition in colorectal cancer." (PMID 29871594, 2018).